KRAS (KRas proto-oncogene, GTPase)
Diseases named in the same sentence as KRAS in open-access papers (continued):
Sharing a sentence is not in itself a finding about the gene and the disease.
colorectal cancer (continued). "Based upon our in vitro results, we propose that a subset of colorectal cancers (CRCs) with mutations in V-Ki-ras2 Kirsten rat sarcoma viral oncogene homolog (KRAS) and Wingless/Integrated (WNT)/beta-catenin signaling might be most sensitive to the effects of hyperthermia as an anti-cancer therapy." (PMID 27187477, 2016). "Importantly, TCGA data analysis revealed that, similarly to lung adenocarcinomas, OTUB1 overexpression in colorectal cancer is mutually exclusive with KRAS mutations (co‐occurrence log odds ratio: −3; P‐value: 0.003), whereas RAS genes are rarely mutated in prostate and breast cancers." (PMID 26881969, 2016). "In colorectal cancer cells KRAS mutations may interfere with ADCC activity." (PMID 26318427, 2015). "This clonal evolution hypothesis has been demonstrated after epidermal growth factor receptor (EGFR)-ablative therapy, where a very low number of Kirsten rat sarcoma viral oncogene homolog (KRAS)-mutated colorectal cancer cells emerged to become the dominant clone among the surviving cells." (PMID 26353782, 2015). "Moreover, this work suggests that a combination of c-Met-targeted therapy with chemotherapy and irradiation might be effective strategies to treat colorectal cancer with KRAS mutations." (PMID 25427200, 2014). "Moreover, the data suggested that the combination of c-Met-targeted therapy with chemotherapy or irradiation might be an effective strategy against colorectal cancer harboring a KRAS mutation." (PMID 25427200, 2014). "However, clinicopathological, molecular, and prognostic features of colorectal carcinoma with KRAS codon 61 or 146 mutation remain unclear." (PMID 24885062, 2014). "Intriguingly, strong Cten expression has been associated with KRAS/BRAF mutations in colorectal cancer, and this association was confirmed as being functionally relevant in colorectal and pancreatic cancers, where Cten has been identified as a downstream target of KRAS signaling." (PMID 24244691, 2013). "When mice bearing colorectal cancer xenografts were treated with cetuximab, the response rates mirrored those seen in clinical trials of cetuximab, and tumors bearing KRAS mutations were resistant to cetuximab, as are most KRAS-mutant colon cancers in human patients." (PMID 23981300, 2013). "However, in CHD-1 colorectal carcinoma cells carrying the KRAS G13D mutation, we could show slight nuclear Abi1 positivity in immunofluorescence microscopy." (PMID 22808230, 2012). "We examined KRAS mutations in exon 2 codons 12 and 13 with DNA sequencing and SNaPshot analysis in 100 formalin-fixed paraffin-embedded tumor tissue samples of pancreatic carcinoma, colorectal carcinoma, and nonsmall cell lung cancer specimens of the primary tumor or metastases." (PMID 21197450, 2010). "Colorectal cancer (CRC) remains a major cause of cancer-related deaths in advanced disease, and activating KRAS/NRAS mutations limit the use of anti-EGFR antibodies to RAS-wild-type tumors." (PMID 41683587, 2026). "Nearly 50% of patients with KRAS-mutant colorectal cancer (CRC) currently lack effective targeted therapy." (PMID 41574609, 2026). "From this series, LS-1-2 emerged as a preclinical drug candidate, demonstrating potent anti-proliferative and anti-metastatic efficacy in both in vitro and in vivo models of KRAS-mutant colorectal cancer." (PMID 41362735, 2026). "Colorectal cancer (CRC) has a high incidence and mortality rate globally, with approximately 40% of patients harboring Kirsten rat sarcoma viral oncogene homolog (KRAS) mutations." (PMID 41362725, 2026). "Together, these data define a macrophage-driven resistance network in KRAS-mutant colorectal cancer organoids and support combined inhibition of RAS-pathway and tyrosine kinase signalling." (PMID 42094384, 2026). "This study describes the application of an automated, modular synthesis platform ('Chemputer') to a drug discovery project targeting a model of KRAS-mutant colorectal cancer (K-CRC)." (PMID 41896327, 2026).
colorectal cancer (continued). "Integrated multi-omics analysis combining phosphoproteomics and RNA sequencing elucidated the mechanism of action of LS-1-2 in KRAS-mutant colorectal cancer." (PMID 41362735, 2026). "Future clinical trials should evaluate this strategy not only in lung cancer but also in other KRAS mutant malignancies, including pancreatic and colorectal cancers, particularly in settings where conventional KRAS-targeted strategies fail." (PMID 41526435, 2026). "Elevated ATP7A expression protects KRAS-mutant colorectal cancer cells from copper toxicity, whereas ATP7A silencing reduces LOX activity and inhibits lung cancer metastasis in mice." (PMID 41480765, 2026). "Background/Objectives: Colorectal cancer (CRC) remains a leading cause of cancer mortality globally, with KRAS mutations occurring in 30–40% of cases, contributing to poor prognosis and resistance to anti-EGFR therapy." (PMID 39941797, 2025). "Background and Objectives: KRAS genes are among the most prominent oncogenes that trigger tumor formation in colorectal cancer (CRC) and serve as predictive biomarkers for resistance to anti-EGFR therapies in metastatic colorectal cancer (mCRC) patients." (PMID 40282985, 2025). "KRAS mutations occur most frequently in pancreatic adenocarcinoma (PAAD, ~90%), followed by colorectal cancer (CRC, 36–40%), cholangiocarcinoma (CHOL, ~27%), and lung adenocarcinoma (LUAD, 15–20%)." (PMID 40427667, 2025). "Therefore, lymph node-targeting amphiphile vaccination induces persistent T cell responses targeting oncogenic driver KRAS mutations, alongside personalized, tumor antigen-specific T cells, which may correlate to clinical outcomes in pancreatic and colorectal cancer." (PMID 40790272, 2025). "Onvansertib is a competitive ATP inhibitor for Plk1 in clinical trials for the treatment of tumors and has recently entered a trial for the treatment of KRAS mutant colorectal cancers (CRCs)." (PMID 40197665, 2025). "Mutated KRAS status was indicated to be a predictor of resistance to cetuximab therapy, not only in NSCLC but also in colorectal cancer, and was associated with a worse prognosis." (PMID 40597785, 2025). "KRAS mutations are most commonly found in non-small cell lung cancer (NSCLC), colorectal cancer, and pancreatic cancer." (PMID 40779492, 2025). "Clinical validation of 95 glioma and 93 colorectal cancer samples showed that IDH1 and KRAS mutations were 100% consistent with Sanger sequencing." (PMID 40650970, 2025).
colorectal cancer (continued). "We revealed that RLY01, with low toxicity, markedly impeded the growth of KRAS-mutant lung cancer organoids in vitro and tumor development in several preclinical mouse models in vivo, including colorectal cancer lung cancer xenografts." (PMID 40091835, 2025). "GSE254832 is the dataset consisting of RNA sequencing data of the HCT 116 colorectal cancer cell line and its KRAS knockdown transfectant." (PMID 40723829, 2025). "Oncogenic mutations in KRAS are critical drivers of colorectal cancer, studies have reported that the upregulation of GLUT1 expression and increased glucose uptake primarily depend on KRAS and BRAF mutations in CRC cells." (PMID 41488637, 2025). "LMF improved 5-FU efficacy in colorectal cancer via distinct mechanisms across wild-type and mutant KRAS." (PMID 41378212, 2025). "Najumudeen observed that KRAS rewires the amino acid metabolism in colorectal cancer (CRC) tumorigenesis through its dependency on SLC7A5, a glutamine antiporter." (PMID 39806421, 2025). "For instance, ER overexpression is correlated with poor prognosis and overall survival in colorectal cancer patients, which is documented to have a significant interplay with oncogenic KRAS." (PMID 41144437, 2025). "In colorectal cancer, mutations in the RAS gene family (mostly KRAS and NRAS) lead to the synthesis of actively functioning RAS proteins." (PMID 40731832, 2025). "Clinically, LZTR1 expression is frequently downregulated in KRAS-driven malignancies such as pancreatic and colorectal cancers, correlating with elevated KRAS stability and MAPK hyperactivation." (PMID 40427667, 2025). "Proteomic analysis of exosomes from DKO-1 cells (isogenic colorectal cancer cells) expressing mutant KRAS revealed the enrichment of tumor-promoting proteins in exosomes compared to those from DKs-8 cells that express only WT KRAS." (PMID 41294676, 2025). "In summary, KRAS plays multiple roles in colorectal cancer, making it an intriguing area for future research and exploration." (PMID 39941797, 2025). "More recently, KRAS was found to accelerate the degradation of dsRNA in colorectal cancer, impairing dsRNA sensing and the interferon response by downregulating DExD/H-box helicase 6 (DDX60)." (PMID 40333779, 2025). "For example, a KRAS (G12C) inhibitor approved by the FDA in 2021 can induce ferroptosis in colorectal cancer cells." (PMID 40721409, 2025). "SLC25A21, an αKG transporter in mitochondria, has been reported to affect the activity of the jmjC-type DNA demethylase TET in KRAS-mutant colorectal cancer." (PMID 41227300, 2025). "For instance, Moderna's mRNA‐5671 (V941) encapsulates mRNA encoding KRAS mutations (G12D, G12V, G13D, and G12C) within LNPs and is currently under clinical evaluation for PDAC, non‐small cell lung cancer, and colorectal cancer." (PMID 40498983, 2025). "In a recent study, Zhou and colleagues identify KRAS, a frequently mutated oncogene, as a negative regulator of dsRNA and viral mimicry in an ICI‐resistant colorectal cancer model." (PMID 39592415, 2025). "Regarding the genetic profiles of colorectal cancer cell lines used in this study, DLD‐1 harbors a KRAS G13D mutation, and WiDr harbors a BRAF V600E mutation." (PMID 40629930, 2025). "The increase in miR-19a suppressed the oncogene KRAS, leading to a reduced formation of new blood vessels, limiting tumor growth and spread in colorectal cancer." (PMID 40871106, 2025).
colorectal cancer (continued). "This perception was shattered recently with the approval of two KRAS inhibitors for the treatment of KRASG12C-mutant lung and colorectal cancer, fueling hope that KRAS inhibitors will lead to a breakthrough in PDAC therapy." (PMID 40829181, 2025). "Together, these studies have positioned KRAS as a critical biomarker in the management of colorectal cancer." (PMID 40575161, 2025). "Both in vivo and in vitro studies show that PDP1 enhances the malignancy of KRAS mutant colorectal cancer cells." (PMID 40746885, 2025). "Colorectal cancer (CRC) is one of the most common cancers worldwide, with KRAS mutations occurring in approximately 40% of cases." (PMID 40361439, 2025). "KRAS (Kirsten rat sarcoma viral oncogene homolog) is a known oncogene in a variety of neoplastic conditions, such as non-small cell lung cancer, colorectal cancer, and pancreatic cancer." (PMID 41010632, 2025). "Focusing on the 37 colorectal cancers with class 3 BRAF mutants and concomitant Ras pathway mutations, only eight harbored typical KRAS mutations (P < 10−5, Fisher exact test)." (PMID 39751654, 2025). "With the widespread application of machine learning (ML) in the diagnosis and treatment of colorectal cancer (CRC), some studies have investigated the use of ML techniques for the diagnosis of KRAS (Kirsten rat sarcoma) mutation." (PMID 40680189, 2025). "This synergism is clinically validated in the KRYSTAL-1 trial: while adagrasib (KRAS G12C inhibitor) monotherapy yielded 16% ORR in colorectal cancer, combination with cetuximab increased ORR to 46%." (PMID 40689200, 2025). "Despite the encouraging initial efficacy of KRAS G12C inhibitors, rapid drug resistance inevitably occurs, and EGFR signaling reactivation is one of the main resistance mechanisms to KRAS G12C inhibitors in patients with colorectal cancer." (PMID 40304209, 2025). "Our study’s aim was to evaluate the clinicopathological profile of colorectal cancer (CRC) patients from North-East Romania in relation to the Kirsten rat sarcoma viral oncogene homolog (KRAS)." (PMID 39996841, 2025). "Persistent efforts focus on resistant tumors such as MSS colorectal cancer and KRAS-driven malignancies." (PMID 40430901, 2025). "Colorectal cancer (CRC) arises through interactions between driver mutations, such as in APC and KRAS, and the tumor microenvironment (TME), including inflammatory factors." (PMID 41285904, 2025). "The KRAS oncoprotein is a frequent tumor driver in lung, pancreatic, and colorectal cancers and has proven to be a challenging pharmaceutical target." (PMID 40517320, 2025). "Previous studies have validated the efficacy of CT-based radiomic models in predicting KRAS, NRAS, and BRAF mutations in colorectal cancer." (PMID 41409606, 2025). "Our study underscores the importance of KRAS therapeutic development, as future discoveries will likely improve survival outcomes of patients with colorectal cancer, particularly those with YO-CRC." (PMID 40940860, 2025).
colorectal cancer (continued). "In conclusion, our study explored the challenging landscape of the KRAS gene, emphasizing its intricate network and molecular heterogeneity across colorectal cancer (CRC) and pancreatic ductal adenocarcinoma (PDAC) patients." (PMID 40013338, 2025). "In KRAS-mutant colorectal cancer, inhibition of the AKT/mTOR signaling pathway enhances tumor cells sensitivity to ferroptosis and significantly inhibit tumor progression." (PMID 41479924, 2025). "Ongoing trials include adagrasib plus cetuximab for KRAS G12C in colorectal cancer (CRC) (phase III) and BLU-945, a fourth-generation EGFR inhibitor, for osimertinib-resistant NSCLC (phase I/II)." (PMID 40547482, 2025). "Diminished infiltration of cytotoxic CD8+ T cells also lowers the sensitivity of KRAS-mutant colorectal cancer to anti-PD-1 therapy." (PMID 41488637, 2025). "Oncolytic reovirus is a potential therapeutic for colorectal cancer patients with a mutant KRAS gene." (PMID 40526688, 2025). "Mutation in the Kirsten rat sarcoma virus (KRAS) gene, a member of the RAS family, has been reported to be an oncogenic driver in multiple solid tumor types, including pancreatic cancer, colorectal cancer, and lung cancer." (PMID 40585984, 2025). "The use of multi-gene panels such as F1LCDx enables identification of other alterations within colorectal cancer (e.g., KRAS) or across tumor types (e.g., NTRK1/2/3) which are relevant to diagnosis and potential treatment options for patients." (PMID 40832988, 2025). "In this study, KRAS-mutant colorectal cancer patients exhibited higher ERα expression levels, whereas ERβ expression tended to be lower than wild-type KRAS patients." (PMID 40282985, 2025). "Many colorectal cancers acquire driver mutations in genes in the MAPK/ERK signaling pathway, including heterozygous missense changes in KRAS, NRAS, or BRAF." (PMID 39751654, 2025). "It has been proved that the lncRNA BCYRN1 affected the occurrence and development of colorectal cancer by regulating the effects of miR-204-3p on KRAS." (PMID 40764575, 2025). "In colorectal cancer, CIMP is linked to the BRAFV600E mutation and to microsatellite instability, while another alternative CIMP, driven by KRAS mutation(+), has been reported in colorectal cancer and linked to adverse patient prognosis." (PMID 40611337, 2025). "Histone lactylation is a novel epigenetic modification derived from lactate, but its role and mechanism in KRAS mutant colorectal cancer (CRC) progression remains to be fully elucidated." (PMID 40707783, 2025). "In a phase 1 study, ELI-002 2P induced significant T-cell and biomarker responses in patients with immunotherapy-recalcitrant KRAS-mutant pancreatic and colorectal cancers with minimal residual disease (MRD)." (PMID 40361439, 2025). "In colorectal cancer cells with mutant KRAS, it-mediated glutaminolysis reduces DNA demethylation to increase WNT Signaling, stemness, and drug resistance." (PMID 40298644, 2025). "Mutations in KRAS and BRAF genes are prevalent in colorectal cancer (CRC), which strikingly promote tumorigenesis and lead to poor response to a variety of treatments including immunotherapy by activating the MAPK/ERK pathway." (PMID 40001243, 2025). "In summary, the functional consequences of KRAS and NRAS mutations in colorectal cancer are multifaceted, influencing not only intracellular signal transduction and therapeutic response but also tumor progression and systemic disease behavior." (PMID 40731832, 2025). "In contrast, vitamin C, another member of vitamin family, inhibits KRAS G12D-driven colorectal cancer." (PMID 39806421, 2025).